AXL (AXL receptor tyrosine kinase)
Diseases named in the same sentence as AXL in open-access papers (continued):
Sharing a sentence is not in itself a finding about the gene and the disease.
tumor (continued). "Due to the high level of AXL expression on many tumor types, antibody-based therapies which specifically target AXL could be beneficial in the clinic." (PMID 32148495, 2020). "The survival of AXL-CAR-T cells was also monitored during tumor elimination." (PMID 31998790, 2020). "AXL could be a powerful actor of the ability of cancer cells to escape the tumor core through its expression in cells at the contact with the stroma and its stimulation by Gas6 secreted in the tumor microenvironment." (PMID 31963783, 2020). "In addition, EGCG + GTE inhibited AXL activation in tumours, which possessed lower levels of ALDH1A1 and SLUG proteins than those of the non-treated group." (PMID 32051483, 2020). "Of the 29 EGFR-mutated NSCLC tumor specimens, high (2+ to 3+) and low (no to 1+) AXL expression was observed in 6 (21%), and 23 (79%) specimens, respectively." (PMID 32929081, 2020). "Notably, five DEG expression levels were correlated with prognosis in these three tumor types, including AXL, CCDC152, EVI2B, GLIPR1, and SERPING1." (PMID 32903590, 2020). "Western blot analysis demonstrated that while the evaluated EGFR-mutated NSCLC cell lines expressed various levels of IGF-1R protein, AXL-low-expressing tumor cells reported higher levels of phosphorylated IGF-1R (pIGF-1R) compared to AXL-high tumor cell lines." (PMID 32929081, 2020). "The review discusses the structure and activation of the Gas6/Axl signaling pathway, GAS6 and AXL expression patterns in the tumor microenvironment, mechanisms of Axl-mediated tumor immune response, and the role of Gas6/Axl signaling in immune cell recruitment." (PMID 32660000, 2020). "In addition, LY2801653 also inhibited the in vivo growth of MET and AXL‐independent cells at higher but clinically relevant doses through decreasing M2 macrophages in the tumor microenvironment." (PMID 34766112, 2020). "AXL receptor tyrosine kinase is a key mediator of tumor invasiveness, particularly in TNBC." (PMID 32210163, 2020). "In addition to the pro-tumorigenic role of AXL on tumor cells, AXL signaling can also suppress anti-tumor immune responses." (PMID 33105713, 2020). "The present study shows exosomes derived from donor cells with high AXL expression could be transmitted to receiver cells with low AXL, and the exosomes transferred intercellularly promoted tumor cells proliferation and invasion." (PMID 32673448, 2020). "Acquired resistance is classified as the progression of tumor after initial tumor regression during the therapy, which is often driven by the development of other pathways stimulating angiogenesis, such as AXL, MET, and PDGF/PDGFR, and thus the escape of cancer cells from VEGF/VEGFR blockade." (PMID 33510766, 2020). "In previous studies, it has been shown that due to the abnormal overexpression of AXL in tumor cells, AXL could be used as a target of solid tumors for CAR-T cells." (PMID 31998790, 2020). "Indeed, hMENA expression not only promotes the secretion of GAS6 in CAFs but also regulates AXL expression and GAS6‐mediated AXL activation in tumor cells." (PMID 32909687, 2020). "Furthermore, exogenous AXL expression stimulated tumour sphere formation in H1703 cells, which express AXL at lower levels than H1299 cells." (PMID 32051483, 2020). "The tumor cells in which AXL was downregulated lost their invasive and migratory characteristics." (PMID 33182542, 2020). "This activation mechanism results in trans-autophosphorylation of multiple tyrosine residues present in AXL’s cytoplasmic domain; three residues (Y779, Y821 and Y866) are involved in tumor development because their activation modulates several downstream effectors." (PMID 33182542, 2020). "Furthermore, we demonstrated axl-148b ability to reduce the percentage of AXL+ cells in the tumor at 18 and 32 days." (PMID 32174798, 2020). "Aberrant Gas6/AXL expression has been described in several tumor types, including RCC." (PMID 33072597, 2020).
tumor (continued). "We also observed that AXL was mainly expressed by tumor cells in contact with the stroma." (PMID 31963783, 2020). "Importantly, results from qRT-PCR also confirmed our in vitro cell lines data showing TR4 can promote lncTASR expression in mice tumor samples to trigger the AXL axis and tretinoin can suppress this axis by targeting TR4." (PMID 31501521, 2020). "Furthermore, the reason why baseline level expression of phosphorylated IGF-1R is higher in the AXL-low-expressing tumor cells than that in the AXL-high-expressing tumor cells is also unclear at present." (PMID 32929081, 2020). "Its oncogenic implications make it an ideal target for the development of new pharmacological agents; moreover, its recent role as immune-modulator makes AXL particularly attractive to researchers involved in the study of interactions between cancer and the tumor microenvironment (TME)." (PMID 33182542, 2020). "As both AXL and NFkB were highly activated in several treatment conditions, including therapy-resistant tumor growth, we sought to determine whether AXL and NFkB phosphorylation were correlated in our models." (PMID 32245042, 2020). "In addition, functional rescue assays revealed that the tumour suppressive roles of LINC00526 are dependent on the negative regulation of AXL." (PMID 31240814, 2019). "However, a major limitation of these approaches is that tumor cells eventually develop resistance and AXL activation is among the mechanisms of acquired resistance to EGFR inhibition in NSCLC treatment." (PMID 31729427, 2019). "This might result in a sustained inhibition and depletion of the AXL from tumor cell surface and enhance the efficacy of targeted anti-AXL therapies in the clinics." (PMID 31171001, 2019). "We found higher AXL and checkpoint ligand expression levels (PD-L1, PD-L2, etc.)in 2-NDBGhigh cells, which points to a possibility that patients with high N/R ratios may have higher AXL and checkpoint ligand expression in their tumor tissues." (PMID 31451693, 2019). "Stress state in the tumor environment has a crucial role in the induction of GAS6/AXL signaling." (PMID 31700829, 2019). "AXL is an archetypal RTK associated with EMT and with worse outcomes in multiple tumor types." (PMID 31681587, 2019). "AXL inhibition using specific siRNA or chemical compounds in tumor cell-derived xenograft (CDX) models and patient-derived xenograft (PDX) models reduced the viability of osimertinib-exposed tumor cells, inhibited the emergence of DT cells, and delayed the recurrence of tumors." (PMID 30651547, 2019). "GemOE tumor cells overexpress the tyrosine kinase receptor, AXL, that binds Gas628." (PMID 31844158, 2019). "Consistent with the results of mRNA analysis, TYRO3 levels in almost all tumours were higher than those in normal urothelium and vesical muscle samples, whereas AXL levels were higher than those in the urothelium in only a few tumours and this protein was abundant in the vesical muscle." (PMID 30765874, 2019). "Many studies have shown that Gas6/AXL plays a big role in promoting tumor metastasis." (PMID 31110076, 2019). "This might result in a sustained inhibition and depletion of the AXL from tumor cell surface and enhance the efficacy of targeted anti-AXL therapies in the clinic." (PMID 31171001, 2019). "Moreover, genetic or pharmacological inhibition of AXL was shown to have the potential of drug resensitization to erlotinib in these tumor models." (PMID 31815659, 2019). "This study highlights again the diverse role of AXL in different cell types, but whether it can function as a tumor suppressor is still unclear." (PMID 31694201, 2019). "Incubation of THP-1 macrophages with tumor cell derived conditioned medium significantly increased M2 polarization and AXL expression, while AXL inhibition could abrogate M2 polarization." (PMID 31694201, 2019).
tumor (continued). "By RNA in situ hybridization the expression of OPN and IL-8 were found to co-localize with the rare population of cells with high AXL expression in normal tissue and, as well, OPN and IL-8 expressing cells were also found in the vicinity of the AXL positive tumor cells in the TNBC tissues." (PMID 29719832, 2018). "Thus, in vivo cells expressing OPN, IL-8 and COL6A3 are co-located with cells expressing AXL in normal and tumor contexts." (PMID 29719832, 2018). "Indeed, pharmacological inhibitors of two genes (ACVRL1 and AXL) are currently the subject of clinical trials in a range of tumour types as prospective anti-angiogenic therapeutics." (PMID 29915322, 2018). "Although a variety of signaling molecules contribute to the invasion and metastasis in GBM, we found notably that AXL/EZH2/TGF-β1 might be a key regulator in tumor invasion, migration, and EMT." (PMID 29642503, 2018). "AXL is expressed in a subset of tumour infiltrating immune cells, primarily macrophages." (PMID 30400835, 2018). "However, we previously reported overexpression of AXL protein in approximately 52% of EAC tumor samples." (PMID 30353671, 2018). "Fresh pre-treatment tumour biopsies were mandatory for PD-L1 and AXL analysis by IHC." (PMID 30400835, 2018). "Importantly, this heterogeneity can have profound consequences for therapy response; when patients eventually acquire resistance to MAPK inhibitors, > 50% of resistant tumours show enrichment for AXL‐high populations." (PMID 28606996, 2017). "To further examine the role of AXL in tumour progression in vivo, we used a xenograft mouse model." (PMID 29259259, 2017). "Hh and AXL pathways are known to play an important role in EGFR resistance through EMT; in one resistant tumor we found that Hh and AXL are concomitantly strongly activated, suggesting that further studies are needed to investigate the interplay between different resistance signaling." (PMID 28416737, 2017). "Thus, understanding the molecular regulation of AXL expression in tumor cells is of great importance." (PMID 28118606, 2017). "Indeed, the only AXL-positive cases with evidence of tumor shrinkage also had positive MET expression." (PMID 29050231, 2017). "However, to associate image-derived downregulation of AXL with inhibition of EMT, more tumor models with different levels of AXL expression and their attenuation with different therapeutic approaches should be performed in future studies." (PMID 29097911, 2017). "We therefore assessed AXL expression in the tumours on various treatment regimes." (PMID 28606996, 2017). "Notably, genetic or pharmacologic inhibition of AXL in the resistant models suppressed cell proliferation, migration, invasion, and tumor growth, and these effects were significantly augmented when AXL inhibition was combined with docetaxel treatment." (PMID 28455956, 2017). "The expression of AXL was significantly correlated with tumor differentiation (P = 0.014)." (PMID 28551766, 2017). "A total of 93 patients (80.2 %) exhibited positive expression of AXL in tumor tissue." (PMID 27172793, 2016). "Notably, pharmacologic inhibition of AXL in mesenchymal tumor cells is sufficient to sensitize these cells to anti-mitotic agents." (PMID 27834845, 2016). "Expression of AXL was found in about 80 % of ESCC tissue, and was significantly correlated with progression of tumor (P<0.001), increased risk of death (Hazard ratio HR [95 % CI=2.09[1.09-4.04], P=0.028], and distant metastasis (odds ratio OR [95 %CI]=3.96 (1.16-13.60), P=0.029)." (PMID 27172793, 2016). "However, when screened in conjunction with heterotypic stromal cells, our study additionally identified SHH, AKT, and IGF1R/AXL inhibitors as KRASG12D-dependent targets in tumor cells." (PMID 27087446, 2016). "AXL inhibition may represent a novel strategy to target cancer cells, as well as tumor-promoting TAMs in TNBC." (PMID 28721387, 2016).
tumor (continued). "This analysis demonstrated that, besides its well-known role in EMT, AXL is strongly co-expressed with genes involved in several immune functions, confirming AXL as a key factor of a gene network that influence both EMT and tumor-associated inflammation in TNBC." (PMID 28721387, 2016). "GAS6/AXL signaling promotes tumor progression and metastasis through multiple mechanisms." (PMID 27834845, 2016). "Future studies elucidating the role of both tumor and macrophage AXL signaling are needed." (PMID 27834845, 2016). "Recent studies have indicated that GAS6/AXL signaling has the potential to influence the tumor vasculature, paracrine crosstalk between tumor cells and bone marrow derived stromal cells, tumor-fibroblast interactions, as well as NK cell and macrophage function." (PMID 27834845, 2016). "Moreover, AXL is expressed within cellular components of the tumor microenvironment where AXL signaling contributes to the immunosuppressive and protumorigenic phenotypes." (PMID 27834845, 2016). "Accumulating evidence suggests that AXL may promote an immunosuppressive phenotype within the tumor microenvironment." (PMID 27834845, 2016). "Furthermore, AXL supports the pro-tumor activity of M2-type macrophages, inducing tumor progression and resistance to chemotherapy." (PMID 28721387, 2016). "In addition, we found that high expression of tumor AXL predicted worse survival in GC patients based on TCGA database." (PMID 27015365, 2016). "Interestingly, the recurrence pattern of patients differed significantly according to expression of AXL in tumor tissue." (PMID 27172793, 2016). "We found that the medium of macrophages treated with the CM derived from AXL-expressing cells, especially from mesenchymal-like cells, was enriched for tumor-promoting mediators, including CCL18, and IL-10, compared with that from macrophages treated with MCF-7-CM." (PMID 28721387, 2016). "AXL has been shown to regulate proliferation and survival in a number of cancers; however, it appears that AXL signaling and overall biological effect differs depending on tumor type." (PMID 27764792, 2016). "Additionally, in vitro co-culture studies have indicated a role for tumor AXL signaling in M2 polarization of THP-1 cells." (PMID 27834845, 2016). "Together, these studies indicated that GAS6/AXL signaling might play an important role in the regulation of tumor growth." (PMID 27834845, 2016). "GAS6 but not AXL was associated with lymph nodes status (p < 0.05) and consequently with tumour stage (p < 0.05) showing a higher expression in more advanced disease (data not shown)." (PMID 25966280, 2015). "In addition, AXL shRNA-containing DDLPS cells were assessed for their tumor-forming capacity in vivo." (PMID 26573603, 2015). "Thus, the results reveal that YD effectively suppressed the growth of H292 and H292-Gef xenograft tumors as well as the expression of AXL in these tumor tissues." (PMID 25760142, 2015). "Overexpression of AXL and PDGFR is associated with aggressiveness and prognosis of a tumor series." (PMID 26225770, 2015). "EMT-associated up-regulation of AXL can drive autocrine interactions with Gas6 produced by endothelial cells, suggesting that autocrine AXL signaling might be a frequent consequence of EMT in many tumor types." (PMID 25337673, 2014). "Considering that many multi-kinase inhibitors under development have AXL as one of their targets, further exploration of the pharmacologic inhibition of this pathway in pre-clinical models, including tumor cells lines with resistance to anti-EGFR drugs, should be pursued." (PMID 25193853, 2014). "AXL inhibition via AXL knockdown studies or through the use of AXL tyrosine kinase inhibitors was able to reverse acquired resistance and 20% of primary tumor samples demonstrated significant upregulation of AXL upon the development of in vivo resistance as compared to pre-treatment samples." (PMID 25337673, 2014).
tumor (continued). "Several tumor samples were examined for genetic AXL aberrations as well." (PMID 25528764, 2014). "MMP9-induction by AXL enhances the invasive capability of tumor cells." (PMID 22570691, 2012). "The molecular mechanisms by which AXL controls tumor invasiveness remain elusive." (PMID 23077658, 2012). "In fact the PI3K/AKT/mTOR pathway may be required for at least some of the tumor-promoting effects of AXL." (PMID 23077658, 2012). "Single-cell data showed AXL expression in a tumour microenvironment, and given that AXL is capable of homophilic interaction if expressed on neighbouring cells, its expression could be responsible for paracrine interaction between tumour cells and cancer-associated microenvironments." (PMID 41511287, 2025). "In addition to its role as a transforming oncogene, AXL has emerged as a promising target for immuno-oncology because of its involvement in modulating innate immune responses and immune surveillance within the tumor microenvironment." (PMID 41166388, 2025). "Thus, we next sought to determine whether AXL inhibition could modulate the tumor immune microenvironment (TME)." (PMID 41009462, 2025). "Moreover, single-cell RNA sequencing technology provides critical insights into the variability of AXL expression among tumor cells, stromal cells, and immune cells within the tumor microenvironment, aiding in the identification of potential resistance biomarkers." (PMID 40003951, 2025). "However, it remains unclear whether the forms of AXL present on tumor cells differ and which form contributes to tumor growth." (PMID 40933570, 2025). "In short, the results show that ZAXL:239 affibody molecules may inhibit GC tumor cell proliferation by blocking GAS6 binding to the extracellular region of AXL, inhibiting activation of downstream signaling factors, inhibiting cell viability, and promoting apoptosis." (PMID 39644434, 2025). "Moreover, high expression of AXL is associated with poor patient survival, and the interaction of AXL with the tumor microenvironment and its role in immune regulation by involving macrophage polarization, T-cell function, and NK-cell activation shows its potential as a therapeutic target." (PMID 40725039, 2025). "Furthermore, we demonstrated that the anti-tumor efficacy was markedly enhanced by co-administration of DSP-0509 with either an IDO1 inhibitor or an AXL inhibitor, although involvement of diverse immune cell except for Tregs and macrophages needs to be examined in the future study." (PMID 39346737, 2024). "Additionally, corin treatment with or without PLX4032 led to increased expression of H3K4Me2, H3K27Ac, DUSP1, and DUSP5, as well as increased expression of markers of apoptosis and tumor hypoxia in BRAFi-R tumors, with associated decreases in the expression of both MITF and AXL." (PMID 38300709, 2024). "Hence, batiraxcept can inhibit GAS6-mediated AXL signaling to exert anti-tumor effects." (PMID 39062902, 2024). "Additionally, a study analyzed AXL expression in tumor specimens of metastatic ccRCC patients treated with Nivolumab following antiangiogenic therapy failure, revealing that high AXL expression correlated with lower treatment response rates and shorter progression-free survival." (PMID 39014460, 2024). "This may be the pathway by which AXL mediates tumour metastasis." (PMID 36982551, 2023). "In addition, GAS6-CAR-T cells could significantly reduce AXL and CK19 double-positive tumor cells, as well as AXL and CD68 double-positive macrophages." (PMID 37475048, 2023). "Similarly, AXL has been shown to confer selective advantage to cancerous cells in tumor progression and simultaneously targeting AXL and MER could show increased benefit for patients." (PMID 37936688, 2023). "In addition, evidence suggests that the Gas6/AXL pathway is involved in tumor therapy resistance." (PMID 37265798, 2023). "This may indicate that AXL is involved in tumor cell migration." (PMID 37265798, 2023).